ENSG00000280614 (novel transcript, similar to YY1 associated myogenesis RNA 1 YAM1)
Gene: Long non-coding RNA gene on chromosome 21 (8,393,419 to 8,394,341, reverse strand). Ensembl gene ENSG00000280614.
Gene Ontology:
Molecular function: structural constituent of ribosome
Cellular component: ribosome